VCAN (versican)
Diseases named in the same sentence as VCAN in open-access papers (continued):
Sharing a sentence is not in itself a finding about the gene and the disease.
breast carcinoma (continued). "Versican/PG-M G3 domain appears to be important in local and systemic tumor invasiveness of human breast cancer and may enhance connectivity between tumor cells and surrounding stromal components, in addition to facilitating neo-vascularization through interactions with VEGF and fibronectin." (PMID 21079779, 2010). "Expression levels of these genes were also examined across various pathological stages of breast cancer, where a stage-dependent increase was observed particularly for CXCR4, BMP1, VCAN, and WNT2." (PMID 41348904, 2025). "In this study, we have highlighted the significance of TGFβ-1, IL19, CXCR4, BMP1, IL1A, VCAN, PDK1, and WNT2 in breast cancer pathology." (PMID 41348904, 2025). "By employing UALCAN, we examined the pattern of expression for TGFβ-1, IL19, CXCR4, BMP1, VCAN, and WNT2 in breast cancer." (PMID 41348904, 2025). "The accumulation of the immunomodulatory matrix proteoglycan versican (VCAN) can predict the exclusion of CD8+ tumor-infiltrating lymphocytes (TILs) in some settings and, thus, is evaluated in breast cancer here." (PMID 40361362, 2025). "Specifically, we observed up-regulation of genes that drive breast cancer metastasis (IL13RA2, MMP3, PTGS1, SYK, VCAN, and FLT1) and downregulation of metastasis-associated suppressor genes (NOTCH3, and HTRA3)." (PMID 41179294, 2025). "Many questions remain regarding the mechanisms that drive VCAN accumulation and the subsequent exclusion of tumor-reactive CD8+ T cells in breast cancer, and answering these questions will build on the findings presented here." (PMID 40361362, 2025). "We compared the TGFβ-1, CXCR4, IL19, BMP1, VCAN, and WNT2 expression in different subtypes of breast cancer, and the results demonstrated that BMP1, and WNT2 were consistently overexpressed in HER-2 subtype." (PMID 41348904, 2025). "Major components of the breast cancer ECM include collagen, fibronectin, laminin, hyaluronic acid, and proteoglycans, such as versican (VCAN)." (PMID 40361362, 2025). "In contrast to the dynamic spectrum of TAM phenotypes in lung and breast cancer, we identified that TAMs in HCC consisted of VCAN+ and C1QC+ TAMs, exhibiting remarkable dichotomy." (PMID 37383234, 2023). "Among these six genes, five were hypermethylated (GABRA5, ZIC5, GRAMD4, RSPH3, and VCAN), and one was hypomethylated (CSMD1) in breast cancer samples of cases compared to controls." (PMID 36627894, 2022). "Previous studies have shown that VCAN is an EMT-related gene, which plays a role in promoting, leukemia, breast cancer, non-small cell lung cancer, and other cancers." (PMID 35812745, 2022). "Both ITGB4 and VCAN are considered to correlate with ECM and promote tumor invasion and metastasis of breast cancer with elevated expression." (PMID 35966872, 2022). "Therefore, versican and TAMs might represent an attractive target for breast cancer therapy." (PMID 31334111, 2019). "Recently, the opposite role of decorin and versican in the regulation of the cross talk between estradiol receptor and EGFR/IGF-IR signaling pathways in estrogen-responsive breast cancers have been discussed." (PMID 29559954, 2018). "hATT-CMs increase versican, CD44, ADAMTS1 and Adipo R1 expression in breast cancer epithelial cells." (PMID 28173833, 2017). "Seven over-expressed breast cancer genes, namely BCAR1, HSD17B1, MMP14, PLAU, SFRP2, SPP1 and VCAN, had increased promoter methylation and their promoters contained the tumor-specific hypermethylated A-6 or A-7 HMRs." (PMID 25706888, 2015). "MDA-MB-468, a human breast cancer cell line with a very high number of EGF receptors, shows less EGFR enhanced when trasfected with versican G3 domain." (PMID 22096483, 2011). "The specific accumulation of versican in breast tissue with high MD and MAMCs only in the presence of malignant transformation and its association with the aggressiveness of the tumor suggests its possible use as molecular marker in non-palpable breast carcinomas." (PMID 21791066, 2011).
breast carcinoma (continued). "Breast cancer cells treated with recombinant COMP or engineered to overexpress COMP exhibited a marked decrease in the epithelial marker CDH1 and an increase in mesenchymal markers such as VIM and VCAN." (PMID 41689303, 2026). "TGFβ-1, VCAN, and IL19 are comparatively expressed more in Luminal subtype of breast cancer." (PMID 41348904, 2025). "The expression pattern of TGFβ-1, IL19, CXCR4, BMP1, VCAN, and WNT2 in different molecular subclasses of Breast Cancer revealed that TGFβ-1, IL19, CXCR4, BMP1, VCAN, and WNT2 mRNA levels are higher in luminal A followed by luminal B, HER2 and Basal-like respectively." (PMID 41348904, 2025). "However, the correlation between VCAN accumulation and tumor-infiltrating CD8+ T cells in breast cancer has been understudied and is the primary focus of this investigation." (PMID 40361362, 2025). "TUBA1B+ TAMs, C1QC+ TAMs and VCAN+ TAMs were more prevalent in HER2+ breast cancer, whereas IL1B+ TAMs, SLC40A1+ TAMs and APOC1+ TAMs were more dominant in ER+ breast cancer, which illustrates the heterogeneity of TAM subtypes in various molecular subtypes of breast cancer." (PMID 39232806, 2024). "In breast cancer, some researchers have discovered that platelet-derived growth factor (PDGF) stimulates arterial smooth muscle cells to express VCAN, leading to an increase in the expression of ECM components in surrounding cells, thereby promoting the growth and metastatic ability of cancer cells." (PMID 37108649, 2023). "The relationship between VCAN and TNC has not been clearly understood yet, although a tissue co-localization of these glycoproteins has been detected in the peritumoural stroma in breast cancer." (PMID 25064447, 2014). "Similarly, two mRNA transcripts were recently shown to act as miRNA sponges: the 3' UTR regions of Versican (VCAN) mRNA in hepatocellular carcinoma (HCC) and of CD44 mRNA in breast cancer cells." (PMID 24216986, 2013). "The importance of the HA-versican interaction is further supported by the observation that versican-HA aggregates, but not HA alone, promote angiogenesis and stromal cell recruitment in a mouse model of breast cancer." (PMID 24213471, 2012). "We found that the elevated expression of decorin and versican by stromal fibroblasts in non-palpable breast carcinomas with MAMCs is positively correlated with the higher expression of ERα and PR by tumor cells." (PMID 21791066, 2011). "The mechanism(s) by which versican facilitates tumor growth and metastatic transformation in breast cancer is not well characterized." (PMID 21079779, 2010). "Most importantly, we report in the present article that expression of the versican G3 domain in a mammary tumor cell line (66c14) that does not normally metastasize to bone is sufficient to promote their spontaneous metastasis to this tissue site." (PMID 21079779, 2010). "The potential role of anti-adhesive molecules such as versican in systemic tumor invasiveness of breast carcinoma has not been extensively evaluated." (PMID 17662123, 2007). "By contrast, the expression of Versican in breast epithelial cells was significantly lower in women with an early pregnancy compared to nulliparous women and to women with a late pregnancy, also independent of subsequent breast cancer occurrence." (PMID 28423605, 2017).
ovarian carcinoma (57 papers, 2009 to 2025). A malignant neoplasm originating from the surface ovarian epithelium. "High VCAN expression, particularly in the stromal tissue surrounding the tumor, is linked to a worse prognosis for ovarian cancer patients." (PMID 41465326, 2025). "In ovarian cancer, for example, the expression of versican in cancer-associated fibroblasts is regulated and significantly upregulated by TGF-beta receptor II and the SMAD signaling pathway." (PMID 37259101, 2023). "TGF-β enhanced the aggressiveness of ovarian cancer cells by upregulating VCAN in cancer-associated fibroblasts (CAF)." (PMID 29747682, 2018). "It enhances the spreading of ovarian cancer cells by upregulating versican gene (VCAN) in cancer-associated fibroblasts (CAFs), through the activation of type II receptor." (PMID 28906427, 2017). "Versican expression is also associated with cancer relapse and poor patient outcome in breast, prostate and many other cancer types including ovarian cancer." (PMID 21541039, 2011). "Additional evidences in early-stage prostatic cancer and ovarian cancer supports the view that versican deposition is associated with progression of disease." (PMID 21791066, 2011). "Additionally, VCAN is considered as a cancer-causing factor in various types of cancer, including pancreatic cancer, myeloma, ovarian cancer, hepatocellular carcinoma, colon carcinoma, glioma and bladder cancer." (PMID 37108649, 2023). "Furthermore, high levels of VCAN and hyaluronic acid have been linked to a poorer prognosis in ovarian cancer patients." (PMID 37108649, 2023). "Co-culture experiments further demonstrated that VCAN upregulation in CAFs enhanced the aggressiveness of ovarian cancer cells." (PMID 38962317, 2024). "Some hub genes (TBX15 and VCAN) are not well known, but have been reported to be highly expressed in many tumors in recent years, such as gliomas, ovarian cancer." (PMID 38520027, 2024). "VCAN is a highly expressed gene in cancers such as bladder and ovarian cancer, and high VCAN expression can lead to poor patient prognosis." (PMID 39012409, 2024). "For example, TGF-b governs cell invasion via upregulation of CAF-derived versican in the tumor microenvironment in ovarian cancer." (PMID 38267923, 2024). "Studies have also shown that VCAN promotes the growth and progression of ovarian cancer by increasing the expression of TGFβ by fibroblasts known as cancer-associated fibroblasts (CAF)." (PMID 37108649, 2023). "Upregulated VCAN promotes the motility and invasion of ovarian cancer cells by activating NF-kB signaling pathway and by upregulating expression of CD44, MMP9, and a hyaluran-mediated motility receptor." (PMID 36361831, 2022). "Upregulation of VCAN in CAFs enhanced ovarian cancer cell motility and invasion potential by activating the NF-κB signaling pathway and upregulated expression of CD44, MMP9 and the hyaluronan mediated motility receptor." (PMID 36203562, 2022). "Up-regulated VCAN promotes motility and invasion of ovarian cancer cells by activating the NF-κB signaling pathway and up-regulating the expression of CD44, matrix metalloproteinase 9, and hyaluronan-mediated motility receptors." (PMID 35812745, 2022). "TGF-β had the ability to enhance the invasiveness of ovarian cancer cells by up-regulating VCAN in fibroblasts (CAF)." (PMID 33836688, 2021). "VCAN was also reported to express significantly higher in severe ovarian cancer than in normal ovarian tissues." (PMID 33604385, 2021). "The expression of versican in some tumor cells showed an increase in bladder cancer, colon carcinoma, ovarian cancer and hepatocellular carcinoma." (PMID 34356118, 2021). "The increased versican levels in cancer patients were shown to diagnose the occurrence of epithelial ovarian cancer and multiple myeloma." (PMID 32825245, 2020). "A study showed that the upregulation of VCAN promoted the migration and invasion of ovarian cancer cells by activating the NF-κB signaling pathway." (PMID 33381592, 2020).
ovarian carcinoma (continued). "Versican has been shown to be a potential biomarker in different cancers such as hepatocellular carcinoma, colon cancer, and recently in ovarian cancer." (PMID 32351878, 2020). "A study had shown that upregulation of VCAN promoted the migration and invasion of ovarian cancer cells by activating the NF-κB signaling pathway." (PMID 33015179, 2020). "The matrix versican secreted by stroma cells promoted cancer cell proliferation by interacting with HA-CD44 signals in ovarian cancer." (PMID 32825245, 2020). "Elevated levels of VCAN have been reported in many types of cancers to date, including prostate cancer 43, melanomas 44, breast 45, ovarian cancer 46 and colorectal cancer." (PMID 31777586, 2019). "Upregulated VCAN promoted the motility and invasion of ovarian cancer cells by upregulating expression of CD44 and receptor of hyaluronic acid-mediated motility (RHAMM)." (PMID 29747682, 2018). "In another study, a higher ADAMTS-1, ADAMTS-5, aggrecan, versican and TIMP-3 expression in malignant ovarian tumors compared to benign tumors was associated with a shorter overall survival in ovarian cancer patients." (PMID 29393911, 2018). "When VCAN gene is upregulated, NF-κB signaling pathway is activated and promotes motility and invasion of ovarian cancer cells." (PMID 28906427, 2017). "Studies in our lab demonstrated that versican is involved in facilitating both ovarian cancer cell and spheroid adhesion to mesothelial cell monolayers." (PMID 26569327, 2015). "Studies of ovarian cancer cells and leiomyosarcoma cells have showed that versican is necessary for the formation of this HA-rich pericellular matrix." (PMID 26539408, 2015). "This further supports a role for CD44 together with HA and versican in a number of key steps needed for ovarian cancer metastasis." (PMID 26569327, 2015). "The addition of sHA prevents the formation of the versican–HA-rich pericellular matrix and inhibits the binding of ovarian cancer cells to the peritoneal wall in vivo." (PMID 26539408, 2015). "Knockdown of versican expression in ovarian cancer cells decreased their motility in vitro and more interestingly also their ability to form experimental metastases after injection into the peritoneal cavity." (PMID 26539408, 2015). "SKOV3 was chosen for functional studies of versican because it replicates well the peritoneal spread of ovarian carcinoma when injected intraperitoneally into abdomens of mice." (PMID 24999371, 2014). "Elevated versican levels have been observed in primary ovarian carcinoma tumors and secondary metastases when compared with normal ovaries." (PMID 23424670, 2013). "VCAN is a mesenchymal marker whose increased expression in ovarian cancer correspond to tumor progression, metastatic dissemination and poorer survival outcome." (PMID 22916288, 2012). "The use of HA oligomers is a potentially attractive reagent to block versican HA interactions as well as local tumor invasion in ovarian cancer but need further in vivo investigation." (PMID 21541039, 2011). "Our most recent data also shows that motile SKOV-3 ovarian cancer cells expressing CD44 also form a HA/versican pericellular matrix." (PMID 21541039, 2011). "Our results suggest that formation of a CD44/HA/versican macromolecular complex promotes the motility and invasion of ovarian cancer cells." (PMID 21541039, 2011). "The dependence of CD44 for the versican and HA-mediated effects was confirmed by the inhibition of pericellular matrix formation as well as versican mediated motility and invasion of ovarian cancer cells following treatment with CD44 neutralizing antibody." (PMID 21541039, 2011). "Increased expression of versican was also identified as a key protein involved in ovarian cancer metastasis." (PMID 21541039, 2011). "In ovarian cancer, versican has been shown to be present in both cancer cells and the peritumoral stroma and increased expression relates with tumor progression and poorer survival outcome." (PMID 21541039, 2011).
ovarian carcinoma (continued). "Our own recent work has shown that HA oligomers can reduce adhesion of ovarian cancer cells to peritoneal cells, and block ovarian cancer motility and invasion induced by versican and HA treatment." (PMID 21541039, 2011). "In addition to anoikis resistance, VCAN was reported to promote invasion of several cancer types, such as gastric and ovarian cancer cells." (PMID 39333870, 2024). "VCAN expression in ovarian cancer was deemed to be overexpressed." (PMID 37845675, 2023). "A subtype of versican, versican V1, has been shown to be an important tumor growth-promoting and metastasis-promoting factor that induces the proliferation and development of ovarian cancer by regulating the inflammatory response in the tumor microenvironment." (PMID 37259101, 2023). "In ovarian cancer, the activation of TGF-β2/SMAD upregulates the expression of CD44, MMP-9, and RHAMM via VCAN expression (encoding the chondroitin sulfate proteoglycan Versican) in CAFs to promote invasion and metastasis." (PMID 36906534, 2023). "The targeting of other related genes, such as MYC and VCAN, may serve as potential therapeutic targets for ovarian cancer." (PMID 35681617, 2022). "For example, TGF- controls the invasion of ovarian cancer by increasing CAF-derived versican." (PMID 36276268, 2022). "TGF-ß modulates ovarian cancer invasion by upregulating CAF-derived versican (VCAN) in the TME." (PMID 36361831, 2022). "Up-regulated VCAN could also promote the invasion and movement of ovarian cancer cells by up-regulating CD44 and activating the NF-κB signaling pathway, matrix metalloproteinase 9 and hyaluronan-mediated movement receptors." (PMID 33836688, 2021). "In addition, versican was previously shown to be increased in malignant stroma surroundings and promoted the growth of several forms of cancer including ovarian cancer." (PMID 34201657, 2021). "Furthermore, the enhanced expression of COL5A1, COL11A1, and VCAN through regulation of TGF-β1 signaling was identified in ovarian cancer metastasis." (PMID 33026975, 2020). "The secretion of versican in the ECM is another means through which CAFs may promote ovarian cancer motility, spreading, and invasion." (PMID 28926101, 2018). "Furthermore, we demonstrated that versican treatment can induce ovarian cancer cell invasion through an ECM barrier." (PMID 21541039, 2011). "The formation of a stabilized HA/versican pericellular matrix surrounding ovarian cancer cells, protects the ovarian cancer cells against the mechanical forces in the peritoneal cavity and enables strong ovarian cancer cell adhesion to CD44 expressed by peritoneal cells." (PMID 21541039, 2011). "In support of this idea, the expression of CD44 is reduced in the high grade ovarian cancers, and the released hyaluronan could be trapped in the stroma by complexing with versican." (PMID 19435493, 2009). "Upregulation of VCAN protein may promote cell motility and the invasiveness of advanced ovarian cancer through activation of the NF-κB signaling pathway and elevated expression of CD44, matrix metalloproteinase-9 (MMP-9), and the hyaluronan-mediated motility receptor." (PMID 35681617, 2022). "In addition, TGF-β enhances ovarian cancer cell invasiveness by up-regulating VCAN in CAFs." (PMID 35812745, 2022). "Among the potential MGL ligands, we identified glycoproteins that are linked to ovarian cancer progression, such as IGFBP7, MUC16, and VCAN, suggesting that MGL expressed by DCs may exert its immunoregulatory role by interacting with distinct cellular and matrix components." (PMID 33019700, 2020). "Therefore, VCAN has the potential to become a promising biomarker for ovarian cancer." (PMID 31336942, 2019). "Several of the analyzed genes (TGFβ-1, IL19, CXCR4, BMP1, VCAN, and WNT2) showed elevated expression across multiple cancer types in pan-cancer datasets, including lung, colon, and ovarian cancers." (PMID 41348904, 2025).